SYNE4 (spectrin repeat containing nuclear envelope family member 4)
Description:
As a component of the LINC (LInker of Nucleoskeleton and Cytoskeleton) complex, involved in the connection between the nuclear lamina and the cytoskeleton. The nucleocytoplasmic interactions established by the LINC complex play an important role in the transmission of mechanical forces across the nuclear envelope and in nuclear movement and positioning (By similarity). Behaves as a kinesin cargo, providing a functional binding site for kinesin-1 at the nuclear envelope. Hence may contribute to the establishment of secretory epithelial morphology by promoting kinesin-dependent apical migration of the centrosome and Golgi apparatus and basal localization of the nucleus (By similarity).
Synonyms: KASH4; C19orf46; FLJ36445; Nesprin-4; Nesp4; DFNB76
Tractability: Antibody: UniProt predicts a signal peptide or a membrane-spanning region.
Gene: Protein-coding gene on chromosome 19 (36,003,282 to 36,008,831, reverse strand). Ensembl gene ENSG00000181392.
Subcellular location: Nucleus outer membrane
Gene Ontology:
Molecular function: protein binding
Biological process: establishment of epithelial cell apical/basal polarity
Cellular component: meiotic nuclear membrane microtubule tethering complex; nuclear outer membrane; membrane; nuclear envelope
Genetic constraint (gnomAD): Loss-of-function variants: 40 observed, 41.61 expected, observed/expected ratio (o/e) 0.96, 90% interval 0.75 to 1.25. The upper end of that interval is the gene's LOEUF score, 1.25, which puts it in group 5 of 6, group 1 being the genes least tolerant of losing a copy. Missense variants: 477 observed, 493.44 expected, observed/expected ratio (o/e) 0.97, 90% interval 0.9 to 1.04. Synonymous variants: 218 observed, 210.14 expected, observed/expected ratio (o/e) 1.04, 90% interval 0.93 to 1.16.
Gene-disease validity (ClinGen):
ClinGen rates the evidence that SYNE4 causes each of these diseases.
nonsyndromic genetic hearing loss (autosomal recessive): Moderate.
Homologues: Orthologues: chimpanzee SYNE4 (98% identical), macaque SYNE4 (91% identical), dog SYNE4 (73% identical), rabbit SYNE4 (71% identical), guinea pig SYNE4 (68% identical), pig SYNE4 (67% identical), mouse Syne4 (66% identical), rat Syne4 (52% identical).
Diseases named in the same sentence as SYNE4 in open-access papers:
SYNE4 is named in the same sentence as 7 diseases in open-access papers, as found by Europe PMC text mining. Sharing a sentence is not in itself a finding about the gene and the disease. The quoted sentences say what the papers report.
hearing loss (9 papers, 2018 to 2024). "Normothermia TTM upregulated 13 genes associated with hearing loss, including Loxhd1, Tecta, Zmiz1, Espn, Gjb2, Sesn3, Bdp1, Hg, Pax3, Rnls, Syne4, P2rx2, and Pou3f4." (PMID 38298897, 2023). "Among the contributors to PDT-EC we identified OSBPL2 and SYNE4, two relatively new hereditary hearing loss genes with a low publication profile." (PMID 35682719, 2022). "Uncertainties remain regarding the durability of the treatment and the time window for intervention in humans, but our results suggest that gene therapy has the potential to prevent hearing loss in humans with SYNE4 mutations." (PMID 33350593, 2021). "In this report we present two members of a family with non-syndromic high frequency sensorineural hearing loss who are homozygous for a novel pathogenic SYNE4 variant c.129-1G>T." (PMID 28958982, 2018). "This case report provides supportive evidence for the causative role of SYNE4 variants in hearing loss by presenting an additional family with a novel DNA variant." (PMID 28958982, 2018). "A single SYNE4 variant co-segregating with hearing loss has recently been reported in two Middle-Eastern families." (PMID 28958982, 2018). "Reports of SYNE4 mutations causing hereditary hearing loss are limited; however, this case is one of the few LINC complex-associated diseases where the pathogenesis is relatively well understood, with both human and mouse models exhibiting well-matched pathologies." (PMID 39519078, 2024). "Mouse models lacking SYNE4 or Sun1 have been shown to exhibit progressive hearing loss associated with DFNB76." (PMID 38525683, 2024).
deafness (4 papers, 2018 to 2024). An inherited or acquired condition characterized by the complete loss of the ability to hear from one or both ears. "Genetic variants in SYNE4, encoding the nesprin‐4 protein, have been shown to cause deafness in humans, and Syne4‐deficient mice show a similar phenotype." (PMID 33350593, 2021). "Identification of this novel variant in SYNE4 further elucidates the genotypic profile of the rare deafness phenotype with which it is associated." (PMID 28958982, 2018). "A novel variant in a rare deafness-causing gene (SYNE4; MIM: 615535) was identified and helps to clarify the genotypic profile of this uncommon form of sensorineural HL." (PMID 28958982, 2018). "Affected members of family 951 mirrored this clinical presentation of progressive, high-frequency HL, lending further support to the association of deafness with the SYNE4 variant." (PMID 28958982, 2018). "We have shown before that Syne4−/− mice show early-onset progressive deafness and that at P14 the nuclei of OHC are dislocated towards the apical surfaces, leading to rapid loss of OHC." (PMID 36211453, 2022). "Syne4 deficiency in humans and mice leads to mislocalization of the OHC nuclei and cell death resulting in deafness." (PMID 36211453, 2022). "Our results provide proof of concept for the development of gene therapy for SYNE4 and other forms of deafness." (PMID 33350593, 2021). "Variants in SYNE4, encoding the protein nesprin‐4, a member of the linker of nucleoskeleton and cytoskeleton (LINC), lead to DFNB76 human deafness." (PMID 33350593, 2021). "In addition, we have shown that a single injection of AAV9-PHP.B encoding Syne4 was sufficient to entirely prevent nuclear mislocalization, OHC loss, and deafness in Syne4−/− mice." (PMID 36211453, 2022). "It is possible that the rescue we observed should only be attributed to OHC transduction, which would strengthen our hypothesis that Syne4 deafness stems primarily from OHC dysfunction and degeneration." (PMID 33350593, 2021). "Interestingly, expression of Syne4, the gene encoding Nesprin-4, is very sparse, and Nesprin-4 deficiency in humans and mice was associated with no phenotype other than deafness." (PMID 36211453, 2022). "To further validate our hypothesis that Syne4 deafness stems predominantly from OHC loss and not impaired IHC function, we examined whether the variability in ABR threshold levels at 12 weeks could be explained by OHC survival." (PMID 33350593, 2021). "In this study, we used Syne4−/− mice as a model of DFNB76 recessive deafness, in order to develop a genetic therapy for this form of human deafness, based on AAV9‐PHP.B as a vector." (PMID 33350593, 2021).
Usher syndrome (1 paper, 2024). A syndromic diseae characterized by the association of sensorineural deafness (usually congenital) with retinitis pigmentosa and progressive vision loss. "Cad99C is homologous to the Usher syndrome gene PCDH15 while Msp300 and koi correspond to the nuclear membrane anchoring genes SYNE4 and SUN1, respectively." (PMID 38412189, 2024).
cancer (1 paper, 2021). A tumor composed of atypical neoplastic, often pleomorphic cells that invade other tissues. "Among them, we verified the difference in expression of PARVG and SYNE4 in 13 pairs of normal tissues and cancer tissues." (PMID 34246261, 2021).
SYNE4 also shares sentences with these, for which no sentence is quoted: infertility disorder (1 paper); mesothelioma (1); tumor (1).